BIN1 (bridging integrator 1)
Description:
Is a key player in the control of plasma membrane curvature, membrane shaping and membrane remodeling. Required in muscle cells for the formation of T-tubules, tubular invaginations of the plasma membrane that function in depolarization-contraction coupling. Is a negative regulator of endocytosis (By similarity). Is also involved in the regulation of intracellular vesicles sorting, modulation of BACE1 trafficking and the control of amyloid-beta production. In neuronal circuits, endocytosis regulation may influence the internalization of PHF-tau aggregates (By similarity). May be involved in the regulation of MYC activity and the control cell proliferation. Has actin bundling activity and stabilizes actin filaments against depolymerization in vitro.
Synonyms: AMPHL; SH3P9; AMPH2; CNM2
Tractability: Small molecule: a structure with a bound ligand is known. Antibody: UniProt places it where antibodies can reach, with medium confidence; its Gene Ontology location is reachable by antibodies, with medium confidence. PROTAC: ubiquitination databases record sites on it; its protein half-life has been measured.
Gene: Protein-coding gene on chromosome 2 (127,048,017 to 127,107,556, reverse strand). Ensembl gene ENSG00000136717.
Subcellular location: Nucleus (Isoform BIN1); Cytoplasm; Endosome; Cell membrane, sarcolemma, T- tubule; Cytoplasm (Isoform IIA)
Subcellular location (Human Protein Atlas): Cytosol
Pathways (Reactome):
Vesicle-mediated transport: Clathrin-mediated endocytosis
Gene Ontology:
Molecular function: actin filament binding; aspartic-type endopeptidase inhibitor activity; identical protein binding; lipid binding; protease binding; protein binding; protein-folding chaperone binding; RNA polymerase binding; tau protein binding; clathrin binding; phospholipid binding; GTPase binding; protein-containing complex binding
Biological process: endosome to lysosome transport; lipid tube assembly; negative regulation of amyloid-beta formation; negative regulation of transcription by RNA polymerase II; nucleus organization; positive regulation of apoptotic process; positive regulation of astrocyte differentiation; regulation of cell cycle process; regulation of neuron differentiation; T-tubule organization; cytoskeleton organization; endocytosis; negative regulation of calcium ion transmembrane transport via high voltage-gated calcium channel; negative regulation of potassium ion transmembrane transport; negative regulation of ventricular cardiac muscle cell action potential; positive regulation of actin filament polymerization; regulation of heart rate by cardiac conduction; establishment of localization in cell; positive regulation of endocytosis; regulation of endocytosis; synaptic vesicle endocytosis
Cellular component: axon; cytoplasm; cytoskeleton; cytosol; lipid tube; membrane; nucleus; RNA polymerase II transcription repressor complex; actin cytoskeleton; axon initial segment; dendrite; endosome; I band; node of Ranvier; plasma membrane; synaptic vesicle; T-tubule; vesicle; Z disc; axon terminus; cerebellar mossy fiber; extrinsic component of synaptic vesicle membrane; glutamatergic synapse; varicosity
Genetic constraint (gnomAD): Loss-of-function variants: 53 observed, 81.59 expected, observed/expected ratio (o/e) 0.65, 90% interval 0.52 to 0.82. The upper end of that interval is the gene's LOEUF score, 0.82, which puts it in group 3 of 6, group 1 being the genes least tolerant of losing a copy. Missense variants: 642 observed, 742.21 expected, observed/expected ratio (o/e) 0.86, 90% interval 0.81 to 0.92. Synonymous variants: 302 observed, 308.35 expected, observed/expected ratio (o/e) 0.98, 90% interval 0.89 to 1.08.
Gene-disease validity (ClinGen):
ClinGen rates the evidence that BIN1 causes each of these diseases.
centronuclear myopathy (autosomal recessive): Definitive. Centronuclear myopathy (CNM) is an inherited neuromuscular disorder characterized by clinical features of a congenital myopathy and centrally placed nuclei on muscle biopsy.
centronuclear myopathy (autosomal dominant): Limited.
Homologues: Orthologues: chimpanzee BIN1 (100% identical), pig BIN1 (97% identical), rat Bin1 (94% identical), guinea pig BIN1 (94% identical), dog BIN1 (87% identical), macaque BIN1 (86% identical), rabbit BIN1 (84% identical), mouse Bin1 (77% identical), tropical clawed frog bin1 (72% identical), zebrafish bin1a (46% identical), zebrafish bin1b (38% identical), Drosophila melanogaster Amph (28% identical). Paralogues in human: AMPH (49% identical), BIN2 (33% identical), BIN3 (10% identical).
Diseases named in the same sentence as BIN1 in open-access papers:
BIN1 is named in the same sentence as 137 diseases in open-access papers, as found by Europe PMC text mining. Sharing a sentence is not in itself a finding about the gene and the disease. The quoted sentences say what the papers report.
Alzheimer disease (104 papers, 2011 to 2026). A progressive, neurodegenerative disease characterized by loss of function and death of nerve cells in several areas of the brain leading to loss of cognitive function such as memory and language. "BIN1 has been repeatedly identified as one of the major genetic risk factors for Alzheimer’s disease, where its dysregulation contributes to abnormal membrane remodeling, Tau pathology, and synaptic loss." (PMID 41516344, 2026). "The Bridging Integrator 1 (BIN1) gene was identified in genome-wide association studies (GWAS) as the second most significant susceptibility locus for late-onset Alzheimer’s disease (LOAD)." (PMID 40835006, 2025). "The differential expression of BIN1 isoforms was observed in the brains of Alzheimer’s disease patients, and the loss of BIN1 parallels myelin loss in multiple sclerosis brain lesions." (PMID 40943121, 2025). "Other known Alzheimer's disease–associated genes, BIN1, TREM2, ZCWPW1, and APH1B, were also replicated in our time-to-event GWAS." (PMID 40949174, 2025). "The siRNA-NP targeting diverse molecular mechanisms implicated in Alzheimer's disease, to downregulate genes such as bridging integrator 1 (BIN1), sortilin-related receptor 1 (SORL1), and clusterin (CLU) has proven useful in various animal models." (PMID 41356731, 2025). "Many studies in recent years in various populations have attempted to demonstrate an association between polymorphism in the BIN1 gene and the risk of Alzheimer’s disease." (PMID 41465142, 2025). "In Alzheimer’s disease, such a model has been presented where too much or too little BIN1 expression are both associated with enhanced risk of disease." (PMID 38664444, 2024). "The bridging integrator 1 (BIN1) gene is an important risk locus for late-onset Alzheimer’s disease (AD)." (PMID 38206965, 2024). "Bridging Integrator 1 (BIN1) is the second most important Alzheimer’s disease (AD) risk gene, but its physiological roles in neurons and its contribution to brain pathology remain largely elusive." (PMID 38514804, 2024). "Bin1, a synaptic gene implicated in Alzheimer’s disease, exemplifies regional specificity in excitatory neurons and temporal regulation at the P21-P28 transition." (PMID 37066387, 2023). "Reduced BIN1 expression and function is a known risk factor for late-onset Alzheimer’s disease, having critical roles in presynaptic release of glutamate and the facilitation of learning and memory." (PMID 37674018, 2023). "Differences in gene-wide DNA methylation of the Alzheimer’s disease (AD)-associated genes BIN1, HLA-DRB5, SORL1, SLC24A4, and ABCA7 are reported to be associated with AD in post-mortem brain samples." (PMID 36573011, 2023). "The BIN1 locus contains the second-most significant genetic risk factor for late-onset Alzheimer’s disease." (PMID 35526014, 2022). "Recently, Schürmann and colleagues used SIM to study the late-onset Alzheimer’s disease risk factor BIN1 and showed that this protein is abundant in postsynaptic compartments, including dendritic spines." (PMID 34830352, 2021). "The bridging integrator 1 (BIN1) gene is the second most important susceptibility gene for late-onset Alzheimer’s disease (LOAD) after apolipoprotein E (APOE) gene." (PMID 33531457, 2021). "De Rossi and colleagues investigated the role of BIN1 (late-onset Alzheimer disease risk factor) function in the brain using conditional knockout (cKO) models." (PMID 34830352, 2021). "LACTB2 and PLIN2 had novel significant associations with Alzheimer’s disease and BIN1, PTK2B, SPI1, MS4A4A, MS4A6E, APOE and PVR are in known Alzheimer’s disease risk loci from GWAS." (PMID 33959712, 2021). "The post‐synaptic protein Bin1 has been identified as a late‐onset Alzheimer's disease‐associated protein." (PMID 33188547, 2021). "Rs7561528, the most significant SNP of the BIN1 gene, is considered a risk factor for late-onset Alzheimer's disease in the Caucasian population." (PMID 34733192, 2021).
Alzheimer disease (continued). "Modelling the loss of BIN1 in Alzheimer’s disease in primary neurons showed that when BIN1 is knocked down, phosphorylated tau accumulates at synapses." (PMID 32500121, 2020). "Polymorphisms associated with bridging integrator 1 (BIN1) increase the risk of Alzheimer’s disease." (PMID 32500121, 2020). "In fact, variants at numerous other genetic loci related to endocytic trafficking and synaptic maintenance have been discovered as risk factors for Alzheimer’s disease (BIN1, PICALM, CD2AP, SORL1) and Parkinson’s disease (SNCA, LRRK2, SH3GL2/EndoA, RAB7L1)." (PMID 32286230, 2020). "Polymorphisms associated with BIN1 (bridging integrator 1) confer the second greatest risk for developing late-onset Alzheimer’s disease." (PMID 32500121, 2020). "Loss of BIN1 from Alzheimer’s disease cytoplasm at moderate and severe stages of disease was accompanied by the accumulation of phosphorylated tau in synaptic compartments." (PMID 32500121, 2020). "Our findings, therefore, suggest that since BIN1 knockdown affects tau release, loss of BIN1 in Alzheimer’s disease will disrupt the functions of extracellular tau in addition to allowing phosphorylated tau to mislocalize to synapses and exert toxicity." (PMID 32500121, 2020). "We confirmed proline 216 in tau as critical for tau interaction with the BIN1-SH3 domain and showed that the phosphorylation of tau disrupts this binding, suggesting that tau phosphorylation in Alzheimer’s disease disrupts tau–BIN1 associations." (PMID 32500121, 2020). "While most genetic variants that increase the risk of Alzheimer’s disease affect β-amyloid generation and/or clearance, BIN1 is relatively unusual in that its effects in Alzheimer’s disease appear to be mediated by tau." (PMID 32500121, 2020). "Genome-wide association studies identified the BIN1 locus as a leading modulator of genetic risk in Alzheimer’s disease (AD)." (PMID 32657270, 2020). "Identified as an Alzheimer’s disease (AD) susceptibility gene by genome wide-association studies, BIN1 has 10 isoforms that are expressed in the Central Nervous System (CNS)." (PMID 32727516, 2020). "Despite Bridging INtegrator 1 (BIN1) being the second most statistically-significant locus associated to Late Onset Alzheimer’s Disease, its role in disease pathogenesis remains to be clarified." (PMID 31263146, 2019). "The single nucleotide polymorphism (SNP) rs744373 in the bridging integrator-1 gene (BIN1) is a risk factor for Alzheimer’s disease (AD)." (PMID 30992433, 2019). "The association between BIN1 rs744373 variant and Alzheimer’s disease (AD) had been identified by genome-wide association studies (GWASs) as well as candidate gene studies in Caucasian populations." (PMID 31874619, 2019). "BIN1, the ortholog of amph-1, has been implicated in the regulation of endocytosis in multiple contexts, even though its specific role in Alzheimer’s disease is unclear." (PMID 30497524, 2018). "Bridging integrator-1 (BIN1) gene is associated with an increased risk to develop Alzheimer’s disease, a tauopathy characterized by intra-neuronal accumulation of phosphorylated Tau protein as paired helical filaments." (PMID 30487734, 2018). "It was also reported that a neuronal BIN1 increase in brain and plasma is associated with Alzheimer’s disease." (PMID 28806752, 2017). "Subsequently, the large IGAP (International Genomics of Alzheimer’s disease Project) study identified further genes encoding the endocytic proteins BIN1 (bridging integrator 1) and SORL1 (sortilin-related receptor) that reached genome-wide significance." (PMID 27430330, 2016). "Genome-wide association studies have identified BIN1 within the second most significant susceptibility locus in late-onset Alzheimer’s disease (AD)." (PMID 27488240, 2016).
Alzheimer disease (continued). "The genes that overlapped with the three other FST peaks were FANCA, a candidate for breast cancer susceptibility, PLAG1 that is associated with stature and body weight, and BIN1 that is associated with Alzheimer’s disease." (PMID 26089079, 2015). "Recent genome-wide association studies of Alzheimer's disease (AD) have identified variants in BIN1, CLU, CR1 and PICALM that show replicable association with risk for disease." (PMID 21347408, 2011). "Two variants at the BIN1 locus are associated with Alzheimer's disease susceptibility below the genome-wide significance level with limited LD between them." (PMID 21390209, 2011). "The associated gene BIN1 is substantially associated with the development of Alzheimer's disease." (PMID 41778964, 2026). "Bridging integrator 1 (BIN1) is one of the strongest genetic risk factors for Alzheimer's disease (AD), yet its function in the brain and role in AD remain unclear." (PMID 41895857, 2026). "Bridging integrator 1 (BIN1) is a genetic risk factor for late-onset Alzheimer disease." (PMID 40889683, 2025). "The gene BIN1 is the second-largest genetic risk factor for late-onset Alzheimer’s disease (LOAD)." (PMID 40835006, 2025). "BIN1 is the second-largest genetic risk factor for late-onset Alzheimer's disease, yet its role in the disease largely remains unclear." (PMID 40835006, 2025). "The prominent Alzheimer’s disease (AD)-associated single nucleotide polymorphisms (SNPs) are located in the BIN1 5′ region, 25 to 30 kb upstream of the coding sequence, indicating that they reside in regulatory or enhancer regions that can confer AD risk by modifying BIN1 expression in brain cells." (PMID 40835006, 2025). "The Bridging Integrator 1 (BIN1) gene is a major susceptibility gene for Alzheimer’s disease (AD)." (PMID 34998435, 2022). "Moreover, we show that BIN1 knockdown in rat primary neurons to mimic BIN1 loss in Alzheimer’s disease brain causes the damaging accumulation of phosphorylated tau at synapses and alterations in dendritic spine morphology." (PMID 32500121, 2020). "Our data provide novel insights into the mechanisms by which BIN1 polymorphisms may increase the risk of Alzheimer’s disease." (PMID 32500121, 2020). "Our results therefore suggest that BIN1 loss in Alzheimer’s disease could reduce the availability of extracellular tau, resulting in a loss of extracellular tau function." (PMID 32500121, 2020). "Our results suggest that BIN1 and tau interact predominantly when tau is dephosphorylated in the cytoplasm and that altered tau phosphorylation, together with BIN1 loss in Alzheimer’s disease, allows tau to be mislocalized to synapses where it is detrimental to synapse health." (PMID 32500121, 2020). "Moreover, recent works suggest that brain amyloid deposition is driven by the APOE locus and that a genome-wide significant variant in the Alzheimer’s disease risk gene BIN1 (rs744373) is associated with tau pathology instead of amyloid pathology." (PMID 32226939, 2020). "Bin1 is strongly linked to Alzheimer's disease, but through Tau and amyloid-β pathology." (PMID 32589750, 2020). "Together, these data show Tau-dependent regulation of neuronal activity by the Alzheimer’s disease risk gene BIN1 and generate new insights about the mechanistic role BIN1 may play in AD." (PMID 32657270, 2020). "BIN1 is the most important risk locus for Late Onset Alzheimer’s Disease (LOAD), after ApoE." (PMID 31408457, 2019). "The bridging integrator 1 gene (BIN1) is a major genetic risk factor for Alzheimer’s disease (AD)." (PMID 31065832, 2019). "Interestingly, human Amph II, also known as bridging integrator 1 (BIN1), has recently been identified as the second most important risk locus for late onset Alzheimer’s disease (AD) by genome wide association studies." (PMID 30135566, 2018).